THAP12 (THAP domain containing 12)
Description:
Upstream regulator of interferon-induced serine/threonine protein kinase R (PKR). May block the PKR-inhibitory function of DNAJC3, resulting in restoration of kinase activity and suppression of cell growth.
Synonyms: p52rIPK; DAP4; PRKRIR; THAP0
Tractability: PROTAC: ubiquitination databases record sites on it.
Gene: Protein-coding gene on chromosome 11 (76,349,898 to 76,381,134, reverse strand). Ensembl gene ENSG00000137492.
Subcellular location (Human Protein Atlas): Cytosol
Gene Ontology:
Molecular function: protein binding; protein dimerization activity
Biological process: negative regulation of cell population proliferation; signal transduction
Cellular component: nucleus
Genetic constraint (gnomAD): Loss-of-function variants: 17 observed, 49.6 expected, observed/expected ratio (o/e) 0.34, 90% interval 0.23 to 0.51. The upper end of that interval is the gene's LOEUF score, 0.51, which puts it in group 2 of 6, group 1 being the genes least tolerant of losing a copy. Missense variants: 529 observed, 808.01 expected, observed/expected ratio (o/e) 0.65, 90% interval 0.61 to 0.7. Synonymous variants: 250 observed, 296.73 expected, observed/expected ratio (o/e) 0.84, 90% interval 0.76 to 0.94.
Homologues: Orthologues: chimpanzee THAP12 (100% identical), macaque THAP12 (99% identical), guinea pig THAP12 (97% identical), rabbit THAP12 (97% identical), pig THAP12 (96% identical), rat Thap12 (96% identical), mouse Thap12 (95% identical), tropical clawed frog thap12 (69% identical), zebrafish thap12b (55% identical), zebrafish thap12a (52% identical). Paralogues in human: ZMYM4 (12% identical), ZBED11 (12% identical), SCAND3 (11% identical), ZMYM3 (11% identical), ZBED8L (11% identical), ZMYM2 (11% identical), GTF2IRD1 (10% identical), ZBED8 (10% identical), EPM2AIP1 (10% identical), ZMYM6 (10% identical), ZBED5 (9% identical), GTF2I (9% identical), and 6 more.
Diseases named in the same sentence as THAP12 in open-access papers:
THAP12 is named in the same sentence as 4 diseases in open-access papers, as found by Europe PMC text mining. Sharing a sentence is not in itself a finding about the gene and the disease. The quoted sentences say what the papers report.
tumor (4 papers, 2015 to 2026). "The LDOC1-H2Bub1 axis, potentially involving THAP12, shapes chromatin accessibility and metastatic transcriptional programs, providing mechanistic and clinical insights into tumor aggressiveness and therapeutic response." (PMID 41484780, 2026).
THAP12 also shares sentences with these, for which no sentence is quoted: cancer (1 paper); diabetes mellitus (1); lung carcinoma (1).